LNCTSI (lncRNA TGF-beta/SMAD3 pathway interacting)
Synonyms: AP000695.1; PTAR; lnc-TSI; lnc-UTGF; AP000695.4; lnc-CHAF1B-2; lnc-CHAF1B-3; AP000695.2; CLDN14-AS1
Gene: Long non-coding RNA gene on chromosome 21 (36,430,289 to 36,627,435, forward strand). Ensembl gene ENSG00000230479.
Diseases named in the same sentence as LNCTSI in open-access papers:
LNCTSI is named in the same sentence as 6 diseases in open-access papers, as found by Europe PMC text mining. Sharing a sentence is not in itself a finding about the gene and the disease.
LNCTSI shares sentences with these, for which no sentence is quoted: ovarian carcinoma (9 papers); serous ovarian cancer (5); tumor (3); colorectal cancer (1); gastric cancer (1); lung carcinoma (1).